IGF1 (insulin like growth factor 1)
Diseases named in the same sentence as IGF1 in open-access papers (continued):
Sharing a sentence is not in itself a finding about the gene and the disease.
diabetes (continued). "Diabetes, as well as HbA1c and serum glucose levels, have been linked to a lower incidence of prostate cancer, partly because of the lower level of insulin-like growth factor-1 levels in diabetic patients, and partly because of the potential detection bias due to the lower PSA level in diabetic men." (PMID 37120669, 2023). "Moreover, it has been suggested that chronic alterations in glucose and IGF-1 levels are risk factors for bone fragility during diabetes, which may lead to bone remodeling and impaired formation, which could be alleviated by several anti-diabetic medications." (PMID 34371877, 2021). "Therefore, decreased expression of IGF-1 can be attributed to insulin deficiency in diabetes." (PMID 33883592, 2021). "However, the underlying mechanisms for impaired IGF-1 production by DETCs in diabetes remain unknown." (PMID 29225596, 2017). "IGF-1 may also increase the risk of an abnormal metabolism and diabetes." (PMID 28954393, 2017). "Although treatment to reduce GH and IGF-1 levels can decrease risk of cardiac hypertrophy and arrhythmias, as well as improve diastolic function, improvements in systolic function and response to exercise depend mostly on disease duration and the presence of hypertension and diabetes." (PMID 27716353, 2016). "Because excessive insulin and IGF-1 signaling by hyperinsulinemia may be one of the most important causes of the development and proliferation of cancer, exogenous insulin is a suspected powerful carcinogenetic factor in diabetes patients." (PMID 25866823, 2015). "The emerging research on colorectal cancer risk for people with diabetes suggests that diabetic patients with poor glycemic control may have even higher risk because they exhibit high levels of circulating insulin and IGF-1 and are often receiving multiple treatments." (PMID 21672406, 2011). "Traditionally, chronic inflammation, hyperinsulinemia, and activation of the insulin-like growth factor-1 (IGF-1) signaling pathway have been considered to link diabetes and pancreatic cancer." (PMID 41601937, 2026). "The highest percentage of children from parents with a high ISCED level was in the “low leptin/IGF-1/HbA1c” status; percentages of familial hypertension, diabetes, and dyslipidemia were lowest." (PMID 39899498, 2025). "Elevated IGF-1 was also tied to lower odds of uncontrolled diabetes, suggesting a possible protective role." (PMID 41393761, 2025). "IGF-1 induced acromegaly-like side effects in clinical trials as a diabetes therapy, and more importantly is a mechanistically distinct intervention from IGF-1R over-expression." (PMID 40171617, 2025). "Disruption of the IIS axis and altered levels of IGF-1 are seen in metabolic disorders like diabetes and metabolic syndrome." (PMID 41393761, 2025). "While insulin-like growth factor-1 is a good alternative, multiple conditions affect its levels, such as diabetes and renal disease, with its concentration varying with age." (PMID 41523526, 2025). "In type 2 diabetes mellitus, hyperinsulinemia and elevated insulin-like growth factor 1 (IGF-1) levels drive activation of the PI3K/Akt/mTOR pathway, enhancing cell survival and proliferation." (PMID 41139205, 2025). "The nomogram includes the following seven variables: IGF-1, C-Peptide, age, diabetes mellitus, total cholesterol, WML, sex." (PMID 39963470, 2025). "The results obtained in this study were as follows: IGF-1, History of Diabetes Mellitus, HbA1c, Insulin, Education Years, SBP, C-Peptide, DBP, Age, Total Cholesterol, Anti-Insulin Antibody, FBG, LDL-C, Triglyceride, White Matter Lesion (WML), and Sex." (PMID 39963470, 2025). "IGF-1 inhibition is being studied as a potential treatment for other endocrine conditions, such as acromegaly and diabetes mellitus." (PMID 40718626, 2025). "After removing liver transaminases and diabetes biomarkers (glucose, IGF1, and HbA1c) from the analysis, our adjusted results remained consistent with the main analyses." (PMID 40738888, 2025).
diabetes (continued). "Overall, the results support IGF-1 as a potential biomarker for identifying uncontrolled diabetes in geriatric patients, warranting validation in larger studies." (PMID 41393761, 2025). "This transcription factor regulates insulin-like growth factor 1 (IGF-1), which has been shown to be reduced in diabetes, along with a decrease in the transcription factor itself." (PMID 40243998, 2025). "According to the nomogram, the total score would be 115 (20 for age, 12.5 for sex, 0 for diabetes, 10 for C-peptide, 40 for IGF-1, 17.5 for total cholesterol, and 15 for WMH)." (PMID 39963470, 2025). "In contrast, some studies suggested that long-term diabetes transitions towards reduced levels of Insulin, IGF-1, and testosterone over time, partially explaining the lower incidence of prostate cancer in men with diabetes." (PMID 41367482, 2025). "To date, only a few studies have investigated the relationship between diabetes during pregnancy and growth factors in colostrum—mainly focused on IGF-1." (PMID 40284249, 2025). "Receiver operating characteristic (ROC) curve analysis identified a cut-off of 7.32 ng/mL for IGF-1, yielding 92% sensitivity and 60% specificity in predicting uncontrolled diabetes." (PMID 41393761, 2025). "In diabetes, however, reduced levels of IGF-1 and TGF-β impair fibroblast and keratinocyte recruitment, hyperglycaemia destabilizes HIF-1α and suppresses VEGF expression, macrophages are dysfunctional, and MMP/TIMP imbalance degrades ECM." (PMID 41614737, 2025). "The significant increase in IGF-1 levels in diabetes treatment suggests the capability of AgNP to enhance insulin secretion." (PMID 39770477, 2024). "Growth Hormone (GH) and Insulin-Like Growth Factor-1 (IGF-1) play intricate roles in the pathophysiology of Type 2 Diabetes Mellitus (T2DM)." (PMID 39578883, 2024). "In summary, the research on Pioglitazone, RRAD, IGF-1, and senolytic therapy highlights the complex interplay between diabetes, aging, and cellular senescence." (PMID 38377027, 2024). "Elevated levels of IGF-1 were found in older patients with dementia and diabetes, yet in another study, lower IGF-1 levels were a predictor of poor cognitive performance in patients with diabetes." (PMID 38398421, 2024). "The distinctive biological features between T1D and T2D imply that different mechanisms contribute to the controversial regulation of IGF-1 in these two types of diabetes." (PMID 38375323, 2024). "The duration of diabetes, age, FPG, FINS, TSH, IGF-1, IGFBP-3, and the serum IGF-1/IGFBP-3 molar ratio levels were independently associated with thyroid nodules in patients with T2DM." (PMID 39444449, 2024). "IGF-1 plays a crucial role in bone metabolism, particularly in patients with diabetes, where osteoporosis is a prevalent and severe complication." (PMID 39398331, 2024). "Metformin was also predicted to indirectly activate IGF-1 and inhibit inflammatory diseases, diabetes mellitus, and CVD through other pathways unrelated to miR-106b-3p." (PMID 38255276, 2024). "The overexpression of IGF1 in vivo significantly reduces the incidence of diabetes, with normal islet beta-cell function and normal insulinemia, indicating that IGF1 regulates islet autoimmunity in NOD mice." (PMID 39590301, 2024). "In this study, we found that there was a significant positive correlation between IGF-1 levels and each of the duration of diabetes (years) and anthropometrical measures." (PMID 38724932, 2024). "The IGF-1/IGF-IR system has been associated with anti-inflammatory properties in the central nervous system (CNS) across various pathologies, including type 1 diabetes mellitus." (PMID 38300646, 2024). "Two, characterizing serum and plasma markers (resorption CTX, formation P1NP, sclerostin, insulin, insulin-like growth factor 1, IL-6, TNFα, etc.)would identify potential metabolic pathways by which diet and diabetes lower the fracture resistance of bone." (PMID 39012489, 2024).
diabetes (continued). "Treatment with IGF-1 reversed diabetes effects and increased total hydroxyproline, DNA, protein, and macrophage in diabetes-induced wound healing impairment." (PMID 39638246, 2024). "Serum IGF-1 levels are reduced in certain conditions such as hypothyroidism, hepatic failure, malnutrition, anorexia nervosa, and poorly controlled type 1 diabetes mellitus." (PMID 39578883, 2024). "It is not entirely clear why dwarf mice live longer, but the assumption is that dwarf mice with a reduced level of growth hormone-IGF1 axis signalling are less prone to cancer and diabetes." (PMID 38992336, 2024). "This is in accordance with other studies showing reduced serum IGF-1 levels in those with diabetes and those with CVD." (PMID 38255276, 2024). "Diabetes mellitus, often a complication of acromegaly, arises mainly from insulin resistance and pancreatic β-cell dysfunction induced by elevated levels of GH and IGF-1." (PMID 39331882, 2024). "Decreases in the serum level of IGF1, similar to insulin, are positively related to the occurrence of type I and 11 diabetes." (PMID 39590301, 2024). "A review has shown that the high IGF-1 concentrations can prevent or delay the inception of diabetes-related complications in people with diabetes." (PMID 38375323, 2024). "Similar to our study they also reported lower IGF-1 levels and higher duration of diabetes in subjects with low BHI SDS." (PMID 38123878, 2024). "The present study observed that IGF-1 levels were diminished in obese patients, while they were elevated in cases of uncontrolled diabetes." (PMID 39578883, 2024). "The present study investigated the potential of the IGF-1/IGFBP-3 molar ratio as a predictor of thyroid nodules in patients diagnosed with type 2 diabetes mellitus." (PMID 39444449, 2024). "The diabetes-related histological and functional changes, as well as fibrogenesis, can be attenuated by IGF-1/IGF-1R inhibition." (PMID 38375323, 2024). "It was that adiponectin and INSR were negative associated with T2D, which reconfirmed the conclusion in previous studies and enhanced the relevance of IGF1 and diabetes." (PMID 38375323, 2024). "The top search terms were: IGF-1, cardiovascular disease, IGF-1 receptors, IGF-1 and microRNAs, therapeutic interventions with IGF-1, IGF-1 and diabetes, IGF-1 and cardiovascular disease." (PMID 36843588, 2023). "Diminished production of pro-angiogenic growth factors, such as IGF-1 and VEGF, is thought to contribute to the impaired angiogenesis in chronic wounds associated with diabetes." (PMID 36981833, 2023). "Already in preclinical models, the consequences of diabetes such as inflammation, hyperglycemia, hyperinsulinemia and increased levels of insulin-like growth factor 1 (IGF-1) have been shown to promote tumor growth." (PMID 37746082, 2023). "Hormonal imbalances due to diabetes lead to decreased insulin-like growth factor 1 (IGF-1) levels, weakening the bones and making joints more susceptible to damage." (PMID 38259415, 2023). "The typical start of prepuberal IR is ∼3–4 years before the pubertal onset, and it is an eventual sign of early evolving diabetes resulting from the cumulative actions of fatness, rising insulin-like growth factor 1 (IGF-1), and adrenal hormones." (PMID 36678200, 2023). "Regarding the nervous system, C/EBPβ overexpression has been shown to improve mitochondrial activity through IGF-1 transcription increase in dorsal root ganglia in the diabetes context." (PMID 36674978, 2023). "Multiple mechanisms including hyperglycemia and decreased signaling by Wnt, adipokine, insulin, or Igf1 have been proposed to impair osteoblast differentiation and function in diabetes, but their functional relevance in vivo remains elusive." (PMID 37144869, 2023).
diabetes (continued). "The high levels of Igf-1 in the skin of mice with diabetes overlapped with those of well-known skin abnormalities caused by elevated plasma concentrations of IGF-1, such as acanthosis nigricans, dermatosis of body folds, and oily skin with keratosis." (PMID 36722656, 2023). "While enhancing insulin sensitivity, growth-promoting properties of IGF-1 are proposed to play a role in developing complications of diabetes." (PMID 37438734, 2023). "Prostate cancer: insulin-deprived environment in long-term diabetes results in a lower amount of insulin-like growth factor-1 receptor (IGF-1R), and higher plasma IGF-1 is associated with a higher risk of prostate cancer." (PMID 35207564, 2022). "The onset of DM may, in part, be explained by the dysregulation of several growth factors, such as IGF-1 in patients with acromegaly, who are at risk of the development of pancreatic cancer as well as diabetes mellitus." (PMID 35954223, 2022). "There are many possible pathways that have been proposed to connect diabetes and cancer, including an increase in insulin/IGF-1 signaling, lipid and glucose uptake and metabolism, alterations in the profile of cytokines and chemokines." (PMID 35976968, 2022). "In contrast, the attenuated IGF-1 signaling that results from defective GH receptors of Laron dwarves seems to confer protection from cancer, stroke, and diabetes while increasing obesity and auditory deficits." (PMID 36063137, 2022). "Still, at all time points, WES compared to CTR sows had lower plasma IGF1 concentrations as observed in patients with a long history of diabetes." (PMID 36079836, 2022). "Studies on patients with diabetes-related foot problems have shown that HBOT can increase the level of IGF-1 in serum, improve diabetic microangiopathy, and promote wound healing." (PMID 36330225, 2022). "Patients with acromegaly characterized by GH hypersecretion display high IGF-1 levels, and acromegaly patients are highly susceptible to IGF-1 related diseases including diabetes mellitus and BPH, suggesting IGF-1 regulation of various diseases." (PMID 35370981, 2022). "Similar to humans, HNF1A-null mice exhibit abnormal glucose-stimulated insulin secretion and develop diabetes two weeks after birth, expressing low levels of insulin and insulin-like growth-factor-1 (Igf1)." (PMID 36361703, 2022). "Patients with diabetes have lower magnesium levels compared to control patients, as IGF1 is able to increase intracellular magnesium levels and also to reverse the dull response of hypertensive cells to insulin." (PMID 35395053, 2022). "The IGF-1 signaling pathway has importance on longevity, and a reduced GH/IGF-1 axis protects from cancer, diabetes, and age-related diseases." (PMID 36589143, 2022). "In this Study, we conducted the serum IGF-1 analysis and the untargeted metabolomic strategy in the population of diabetes with lung cancer and nodules." (PMID 36329881, 2022). "In diabetes, there is also a resistance to IGF-1-mediated myocardial responses, which can be because of increased NOS activity or because of altered protein tyrosine phosphatase activity." (PMID 35454166, 2022). "Hyperglycemia, increased bioactivity of insulin-like growth factor 1, hyperinsulinemia, dysregulation of sex hormones, oxidative stress, and chronic inflammation are some of the biological mechanisms linking diabetes and cancer." (PMID 36620236, 2022). "Furthermore, although several studies have reported possible mechanisms underlying diabetes and cancer, such as hyperglycemia, hyperinsulinemia, and increased activity of insulin-like growth factor 1(IGF-1), the role of FI in the association between T2DM and cancer remains unclear." (PMID 35530326, 2022). "Still, some metabolic dysfunctions occurred, as indicated by the significantly lower IGF1 concentrations as well as an activation of diabetes mellitus–related pathways in muscle tissue of WES compared to CTR animals." (PMID 36079836, 2022).
diabetes (continued). "Another study on patients with diabetes reported that serum IGF-1 levels and BMD at lumbar spine and femoral neck were independent factors associated with prevalent vertebral fracture." (PMID 36010307, 2022). "A significant main effect of vibration was detected for RANK-L (p=0.0003) and CTX (p=0.00002), and a significant diabetes versus vibration interaction was detected for IGF-1 (p<0.00001), with a trend observed for RANK-L (p=0.07)." (PMID 36060973, 2022). "It is clear that diabetes is influenced by IGF-1 because of its effect on pancreatic β-cell function." (PMID 35370981, 2022). "Insulin-like growth factor-1 (IGF-1) is involved in the pathogenesis of metabolic disorders related to diabetes and its complications." (PMID 35122679, 2022). "IGF-1 is mainly produced and secreted by hepatocytes, and patients with diabetes mellitus have significantly decreased IGF-1 levels and reduced bone formation." (PMID 36589835, 2022). "A study on patients with diabetes reported that serum IGF-1 levels were positively correlated with BMD at femoral neck and total hip and were negatively correlated with the FRAX-MOF and FRAX-HF." (PMID 36010307, 2022). "Low IGF-1 levels not only affect BMD but also results in the onset of type 1 or 2 diabetes mellitus." (PMID 35328013, 2022). "The aim of this study was to explore the underlying metabolites changes in diabetes with NSCLC or benign nodule patients, and further to investigate the association of serum IGF-1 level and differentially expressed metabolites (DEMs)." (PMID 36329881, 2022). "Recent studies also report IGF-1-mediated upregulation of mitochondrial respiration together with a dose-dependent stimulation of ATP production through AMPK in a type 1 model of diabetes." (PMID 36002781, 2022). "Insulin-like growth factor 1 (IGF-1) at high concentrations is seen to lower blood glucose levels in case of diabetes characterized by severe IR." (PMID 35600578, 2022). "The delay can also be related to an apparently normal GH concentrations or IGF-1 levels due to pre-existing illness, such as renal failure and diabetes mellitus, leading to false negatives upon testing." (PMID 35207363, 2022). "In fact, the dysregulation of IGF1 and IGF1R levels has been described in association to hyperglycemia in diabetes, including T1DM, and several diabetic complications." (PMID 36506063, 2022). "The application of more biologically active molecules such as alendronic acid, prostacyclin, or insulin-like growth factor 1 (IGF1) can address impaired healing associated with osteoporosis and diabetes in aged patients." (PMID 35456448, 2022). "On the contrary, other studies reported an association between low levels of IGF‐1 and conditions like CVD, diabetes mellitus, osteoporosis, and sarcopenia although a causal relationship has not been established." (PMID 35048526, 2022). "Studies have shown that IGF-1 levels are lower in the serum and liver but increased in the kidneys in patients with diabetes." (PMID 35976968, 2022). "As a matter of fact, diabetes is characterized by hepatic GH resistance and high levels of IGFBPs, which result in decreased levels of total and free IGF-1 levels." (PMID 35454166, 2022). "Drugs/inhibitors or molecules targeting the IGF-1/IGF-1R signaling axis which affect diabetes and intraocular malignancy." (PMID 36003786, 2022). "Initial studies revealed persistent Igf1, Igf2, Ins, and IR transcript levels in the retina and liver during postnatal development and experimental diabetes." (PMID 33915127, 2021). "In this study, we investigated the relationships between serum IGF-1 levels and psychiatric symptoms in patients with chronic schizophrenia and analyzed the association between serum IGF-1 levels and diabetes, antipsychotic drug use, and duration of illness." (PMID 33746806, 2021).